HOXA4 (homeobox A4)
Description:
Sequence-specific transcription factor which is part of a developmental regulatory system that provides cells with specific positional identities on the anterior-posterior axis. Binds to sites in the 5'-flanking sequence of its coding region with various affinities. The consensus sequences of the high and low affinity binding sites are 5'-TAATGA[CG]-3' and 5'-CTAATTTT-3'.
Synonyms: HOX1D; HOX1
Tractability: No criterion of Open Targets' tractability assessment is met for any kind of drug.
Gene: Protein-coding gene on chromosome 7 (27,128,507 to 27,130,780, reverse strand). Ensembl gene ENSG00000197576.
Subcellular location: Nucleus
Subcellular location (Human Protein Atlas): Nuclear bodies
Pathways (Reactome):
Developmental Biology: Activation of anterior HOX genes in hindbrain development during early embryogenesis
Gene Ontology:
Molecular function: sequence-specific double-stranded DNA binding; DNA-binding transcription factor activity, RNA polymerase II-specific; RNA polymerase II cis-regulatory region sequence-specific DNA binding; DNA binding; DNA-binding transcription factor activity
Biological process: anatomical structure morphogenesis; anterior/posterior pattern specification; embryonic skeletal system morphogenesis; positive regulation of transcription by RNA polymerase II; regulation of DNA-templated transcription
Cellular component: nuclear body; chromatin; nucleoplasm; nucleus
Genetic constraint (gnomAD): Loss-of-function variants: 29 observed, 19.34 expected, observed/expected ratio (o/e) 1.5, 90% interval 1.11 to 1.9. The synonymous counts are far from expectation, so gnomAD's model fits this gene poorly and the ratio says little. Missense variants: 402 observed, 314.52 expected, observed/expected ratio (o/e) 1.28, 90% interval 1.18 to 1.39. Synonymous variants: 194 observed, 142.12 expected, observed/expected ratio (o/e) 1.37, 90% interval 1.21 to 1.54.
Homologues: Orthologues: chimpanzee HOXA4 (99% identical), macaque HOXA4 (97% identical), dog HOXA4 (90% identical), rat Hoxa4 (70% identical), mouse Hoxa4 (69% identical), rabbit HOXA4 (56% identical), tropical clawed frog hoxa4 (43% identical). Paralogues in human: HOXB4 (42% identical), HOXD4 (41% identical), HOXC4 (41% identical), HOXA5 (28% identical), HOXB5 (28% identical), HOXB6 (25% identical), HOXA7 (25% identical), HOXC5 (24% identical), HOXA1 (23% identical), HOXA3 (23% identical), HOXA6 (23% identical), HOXB8 (23% identical), and 30 more.
Diseases named in the same sentence as HOXA4 in open-access papers:
HOXA4 is named in the same sentence as 56 diseases in open-access papers, as found by Europe PMC text mining. Sharing a sentence is not in itself a finding about the gene and the disease. The quoted sentences say what the papers report.
ovarian carcinoma (12 papers, 2010 to 2025). A malignant neoplasm originating from the surface ovarian epithelium. "Another potentially relevant circuit for tumorigenesis, in particular for ovarian cancer, a leading cause of death from gynecologic malignancies, is composed of HoxA4, miR-125b and ERBB3." (PMID 20731828, 2010). "Also, higher expression of HOXA4 was associated with a shorter progression‐free survival in 71 patients with ovarian cancer undergoing adjuvant platinum‐based chemotherapy (HR 1.20, 95% CI 1.07–1.34)." (PMID 40420697, 2025). "Overexpression of HOXA4 was suggested to enhance resistance to multiple platinum compounds and potentially reduce the production of reactive oxygen species (ROS) in ovarian cancer cell models." (PMID 40420697, 2025). "In ovarian cancer, several studies reported that HOXA4 plays an important role in cell motility, spreading and cell-cell adhesion." (PMID 23484077, 2013). "An in vitro comparison of ovarian carcinoma cell lines showed that cells exhibiting higher levels of HOXA4 expression have decreased motility by scratch assay." (PMID 21627813, 2011). "In contrast, HOXA4 is known to be a tumor suppressor gene in lung and ovarian cancers." (PMID 37834206, 2023). "The involvement of HOXA4 in colorectal cancer and epithelial ovarian cancer has been reported." (PMID 29700285, 2018). "HOXA4 overexpression suppressed cell motility and spreading in ovarian cancer." (PMID 29631562, 2018). "There is literature evidence that the abnormal expression of HOXA family genes including HOXA4 and HOXA5 is closely related to the occurrence and development of diverse human cancers including breast cancer, colorectal cancer and ovarian cancer 7-9." (PMID 35370463, 2022). "Using small interfering RNA targeting HOXA4, forced expression of full-length HOXA4 and HOXA4-positive and -negative ovarian cancer cell lines, we confirm our previous findings that the ~30-33 kDa band is non-specific and that HOXA4 is detected at ~37-39 kDa." (PMID 22168796, 2011).
lung carcinoma (10 papers, 2018 to 2025). "HOXA4 is associated with various cancer types and its downregulation leads to inhibition of growth and invasion of lung cancer cells." (PMID 33193662, 2020). "As analyzed by Fisher’s exact test, we found that HOXA4 expression in lung cancer was significantly associated with tumor size (P = 0.0262), TNM stage (P = 0.0088) and lymph node metastasis (P = 0.0076)." (PMID 29700285, 2018). "Gene set enrichment analysis (GSEA) was performed to evaluate pathways that were associated with HOXA4 expression in the TCGA lung cancer samples." (PMID 29700285, 2018). "We also observed that HOXA4 expression in lung cancer was significantly associated with tumor size, TNM stage, lymph node metastasis and overall survival." (PMID 29700285, 2018). "HOXA4 is overexpressed in colorectal cancer and epithelial ovarian cancer, and its overexpression can inhibit cancer cell growth and invasion which is associated with Wnt pathway in lung cancer." (PMID 33644115, 2021). "In summary, down-regulation of HOXA4 was associated with poor prognosis of lung cancer." (PMID 29700285, 2018). "Collectively, these data suggest that HOXA4 is a potential diagnostic and prognostic marker in lung cancer, and its overexpression could inhibit lung cancer progression in part by promoting GSK3β transcription." (PMID 29700285, 2018). "A recent report uncovered that HOXA4 affected lung cancer progression by inhibiting the Wnt-b-catenin signaling through GSK3B up-regulation." (PMID 37898994, 2024). "In lung cancer, HOXA4 was downregulated and inhibited the cell growth by promoting the transcription of GSK3β, thereby inhibiting Wnt signaling." (PMID 33479226, 2021). "In the present study, we explored the effects of HOXA4 expression levels on the growth, migration and invasion of lung cancer cells by manipulating HOXA4 expression with lentiviral transduction." (PMID 29700285, 2018). "Transwell assays with or without Matrigel were performed to determine the influence of HOXA4 on lung cancer cell invasion and migration, respectively." (PMID 29700285, 2018). "We then performed functional characterization of HOXA4 in human lung cancer cell lines with HOXA4 overexpression or silencing." (PMID 29700285, 2018). "Cell Count Kit-8 (CCK-8) assays were carried out to explore the functions of HOXA4 regarding lung cancer cell proliferation." (PMID 29700285, 2018). "To investigate the biological implications of HOXA4 in lung cancer, we first analyzed the mRNA and protein expression levels of HOXA4 among 5 lung cancer cell lines and 1 normal lung epithelium cell line via qRT-PCR and western blot." (PMID 29700285, 2018). "We found that HOXA4 levels were significantly lower in lung cancer tissues compared with normal lung tissues." (PMID 29700285, 2018). "Further, quantitative reverse transcription-PCR (qRT-PCR) analysis was performed to examine the expression of HOXA4 in lung cancer samples and adjacent normal tissues obtained from patients at our hospital." (PMID 29700285, 2018). "Kaplan–Meier analysis and the log-rank test were then conducted to assess the relationship between HOXA4 expression and the outcomes of lung cancer patients after surgery." (PMID 29700285, 2018). "Although it has been reported that the Hoxa4 gene is involved in the patterning of the mouse lung during embryonic development, little is known about the biological functions of HOXA4 in lung cancer." (PMID 29700285, 2018). "The ectopic expression of HOXA4 in lung cancer cells decreased cell proliferation, migration and invasion as well as Wnt signaling." (PMID 29700285, 2018). "The expression of HOXA4 was significantly down-regulated in lung cancer cell lines, especially in the NCI-H1975 and NCI-H446 cell lines." (PMID 29700285, 2018). "Annexin V staining followed by cytometry analysis was performed to explore the effects of HOXA4 on lung cancer cell apoptosis." (PMID 29700285, 2018).
lung carcinoma (continued). "The 100 lung cancer patients were split into two groups: the HOXA4 high expression group and HOXA4 low expression group." (PMID 29700285, 2018). "Our study showed that HOXA4 overexpression repressed the growth, motility and invasion of lung cancer cells and inhibited the Wnt pathway." (PMID 29700285, 2018). "Similarly, hypermethylation of CpG sites in the HOXA3/HOXA4 region has been detected in lung cancer." (PMID 38311789, 2024). "Conversely, HOXA4 serves as a tumor suppressor gene in lung cancer and BC." (PMID 38311789, 2024). "There have been already some reports showing HOXA4 is related to lung cancer development 30 or adipocyte differentiation 31, but the vascular function of HOXA4 is largely unknown." (PMID 32147946, 2020). "Moreover, HOXA4 overexpression in lung cancer cell lines suppressed cell proliferation, migration, and invasion." (PMID 29700285, 2018). "Expression of the major component in the Wnt pathway (glycogen synthase kinase-3β [GSK3β]) and downstream effectors of the Wnt pathway (β-catenin, Cyclin D1, c-Myc, and Survivin) was assessed by western blot in lung cancer cells in which HOXA4 had been overexpressed or knocked down." (PMID 29700285, 2018). "To test this hypothesis, we analyzed the expression of HOXA4 in the TCGA lung cancer dataset and our own patient cohort." (PMID 29700285, 2018). "The results revealed that HOXA4 expression was negatively correlated with cell cycle, metastasis and the Wnt signaling pathway, which implied that HOXA4 may affect the growth, invasion and migration of lung cancer." (PMID 29700285, 2018). "Ectopic expression of HOXA4 led to an obvious decrease in the protein levels of downstream effectors of the Wnt pathway (β-catenin, Cyclin D1, c-Myc, and Survivin), which are involved in the development of lung cancer." (PMID 29700285, 2018). "Although other members of the HOX gene family, such as HOXA5, HOXA10, HOXB3, HOXB4, and HOXC618,19, have been found to be overexpressed in lung cancer tissues compared with normal tissues, little is known about the expression and biological function of HOXA4 in lung cancer." (PMID 29700285, 2018). "Our findings suggest that HOXA4 may be a potential therapeutic target for lung cancer." (PMID 29700285, 2018). "In this study, we demonstrated that HOXA4 was down-regulated in lung cancer tissues compared with non-cancerous tissues." (PMID 29700285, 2018). "In the current study, HOXA4 expression was down-regulated in lung cancer tissues when compared with non-cancerous tissues." (PMID 29700285, 2018). "Additionally, HOXA4 binds to the promoter region of ARHGAP25, exerting regulatory control over its transcriptional activity and influencing the growth, invasion, and migration of lung cancer cells." (PMID 38311789, 2024). "However, HOXA4 expression was not correlated with age (P = 0.6845), gender (P = 0.4230), or smoking status (P = 0.5269) in lung cancer." (PMID 29700285, 2018).
breast carcinoma (5 papers, 2008 to 2025). "Moreover, STAC2, AKR1C2, and HOXA4 can be used as the specific prognostic markers for LumB-subtype breast cancer." (PMID 33644115, 2021). "In breast cancer, HOXA4 exhibits increased DNA methylation and decreased gene expression." (PMID 33644115, 2021). "CNTD2, NEURL, STAC2, IL6, FREM1, and HOXA4 may be involved in recurrence of LumB-subtype breast cancer." (PMID 33644115, 2021). "Although little is known about HOXA4 in breast cancer currently, the co-occurrence of HOXA3, A4, A5 and A7 in these rules identified an intimate expression relationship between HOXA4 and the other three HOXA genes, suggesting its potential role in carcinogenesis." (PMID 31703610, 2019). "The data suggested that IL6 and HOXA4 may play key roles in LumB-subtype breast cancer." (PMID 33644115, 2021). "In the selected key specific DEGs for LumB-subtype breast cancer, the expression of CNTD2, NEURL, STAC2, AKR1C2, IL6, FREM1, and HOXA4 were significantly correlated with the prognostic survival of the patients." (PMID 33644115, 2021). "Here, IL6 and HOXA4 were found to be specifically downregulated, and their low expression predicted low RFS in LumB-subtype breast cancer (p < 0.05), and the prognostic analysis result of IL6 was consistent with tha in all breast cancer." (PMID 33644115, 2021).
glioma (5 papers, 2021 to 2025). A benign or malignant brain and spinal cord tumor that arises from glial cells (astrocytes, oligodendrocytes, ependymal cells). "ChIP analysis of randomly selected genes (HOXA4, HOXA‐AS2, and HOXD13) confirmed the marked H3K27me3 loss associated with H3K4me3 and H3K9ac enrichment in seven IDHwt glioma samples from our cohort." (PMID 33720519, 2021). "Finally, the overexpression of HOXA4 promotes cell proliferation and stem cell self-renewal in tumors such as glioma and colorectal cancer." (PMID 40136427, 2025). "A recent study found that HOXA4 knockdown could block cell cycle pathway and inhibit the proliferation, invasion, and chemotherapy resistance in gliomas." (PMID 37334354, 2023). "Other mitochondrial genes such as ABCC3, HOXA4, HOXC10, NNMT, and SCNN1B are typically increased in their expression as the grade of glioma and the higher expression of these genes have been associated with poor prognosis in LGG." (PMID 39012280, 2024). "Furthermore, HOXA4 has been identified as being upregulated in GBM and glioma cells, with its expression levels strongly correlating with a poor prognosis." (PMID 38311789, 2024). "Previous studies have demonstrated the function of ABCC3, HOXA4, HOXC10, and NNMT in gliomas." (PMID 37334354, 2023).
acute myeloid leukemia (4 papers, 2013 to 2021). Acute myeloid leukemia (AML) is a group of neoplasms arising from precursor cells committed to the myeloid cell-line differentiation. "A previous study identified HOXA4 as the only prognostic gene in acute myeloid leukemia (AML), the upregulation of which in patients with normal karyotypes was actually associated with longer‐term survival." (PMID 34606634, 2021).
leukemia (4 papers, 2013 to 2022). A malignant (clonal) hematologic disorder, involving hematopoietic stem cells and characterized by the presence of primitive or atypical myeloid or lymphoid cells in the bone marrow and the blood. "Methylation of a HOX gene, HOXA4 has been strongly associated with progression to blast crisis and poor response to treatment in other types of leukemia patients." (PMID 23484077, 2013). "Evidence shows that HOTAIRM1 is a critical regulator for the expression level of HOXA1 and HOXA4, which is involved in cell growth in leukemia cells." (PMID 30728826, 2018). "In addition, we have demonstrated that treatment of chronic lymphocytic leukaemia patients, results in selection for altered methylation of a number of genes, including hypermethylation of HOXA4, in the leukaemia cells." (PMID 35354948, 2022). "There are reports correlating hypermethylation of HOXA4 with the development of leukemia." (PMID 23484077, 2013). "Furthermore, HOXA4 hypermethylation has been demonstrated to be usually associated with the progression of CML to blast phase and play an important role in the development of leukemia." (PMID 23484077, 2013). "We identified differential methylation of genes that have been related to cancers such as lymphoma (WNT6, TP73, and CD37), leukaemia (MEIS1, HOXA4, and HOXA5) or neuroblastoma (TP73), as well as genes related to cardiovascular diseases (UCN, PRDM16, TCAP, ALOX5)." (PMID 35354948, 2022).
hypospadias (3 papers, 2019 to 2023). Hypospadias is the displacement of the urethral meatus on the ventrum of the penis. "Among these associated genes, HOXA4 mutations have been found in cases of hypospadias and showed a direct link to this malformation." (PMID 31856834, 2019). "Mutation of BMP4 and BMP7—two factors that play a role in normal urethra development, along with HOXA4 and HOXB6, were identified in Chinese patients with hypospadias, but without a clear association." (PMID 37238140, 2023).
microtia (3 papers, 2020 to 2026). "In the investigation of genetic-related diseases, abnormal expression of HOXA4 has been observed, with mutations in HOXA4 being associated with microtia-atresia, a rare congenital condition." (PMID 38311789, 2024). "Among these, HOXA4 (c.920A>C, p.H307P) was determined as the most likely pathogenic variant for microtia-atresia." (PMID 33193662, 2020). "The HOXA4(c.920A > C, p.H307P) substitution was commonly detected in three families, indicating a causative role in microtia-atresia." (PMID 33193662, 2020). "The HOXA4 gene has been identified as potentially pathogenetic for microtia-atresia in three twin families." (PMID 42201244, 2026).
myocardial infarction (3 papers, 2025 to 2026). Gross necrosis of the myocardium, as a result of interruption of the blood supply to the area, as in coronary thrombosis. "Guided by GWAS implicating miRNAs in myocardial infarction, we identified miR-150 as a key effector, finding that hAMSC upregulated cardiac miR-150 and suppressed HOXA4, a profibrotic target in ischemic myocardium." (PMID 42047346, 2026). "Overexpressing HOXA4 exacerbates remodeling after a heart attack, whereas overexpressing miR-150 protects against fibrosis." (PMID 41181801, 2025). "Previous studies indicate that miR-150 mitigates adverse remodeling and fibrosis following myocardial infarction by targeting pro-fibrotic genes such as Hoxa4 and apoptosis-related genes like Gdap1l1, thereby improving cardiac function." (PMID 41300398, 2025). "Myocardial infarction-associated transcript (MIAT), a long non-coding RNA upregulated in failing hearts, inhibits microRNA-150 (miR-150), which typically suppresses HOXA4 expression." (PMID 41181801, 2025).
abdominal aortic aneurysm (2 papers, 2011). Enlargement and ballooning of the vessel that supplies arterial blood to the abdomen, pelvis and legs. "The HOXA4 transcript levels were significantly decreased in human abdominal aortic aneurysms (AAAs) compared to age-matched non-aneurysmal controls (P < 0.00004)." (PMID 21627813, 2011).
acute leukemia (2 papers, 2019). A clonal (malignant) hematopoietic disorder with an acute onset, affecting the bone marrow and the peripheral blood. "HOXA4 promoter hypermethylation and reduced expression have been linked to acute leukemias and a shorter survival." (PMID 31259468, 2019).
acute promyelocytic leukemia (2 papers, 2017 to 2019). An aggressive form of acute myeloid leukemia (AML), characterized by arrest of leukocyte differentiation at the promyelocyte stage, due to a specific chromosomal translocation t(15;17) in myeloid cells. "Recently, HOXA-AS2, a long non-coding RNA located between the HOXA3 and HOXA4 genes in the HOXA cluster, has been characterized as an oncogene in various cancers, including acute promyelocytic leukemia and gastric cancer." (PMID 28388535, 2017).